IL4 (interleukin 4)
Diseases named in the same sentence as IL4 in open-access papers (continued):
Sharing a sentence is not in itself a finding about the gene and the disease.
Zinc deficiency (8 papers, 2010 to 2025). A deficiency of the essential metal Zinc; an essential cofactor for many enzymes. "Since the IL-4-induced pathway is essential for the immunoglobulin (Ig) class switch to IgE, altered signaling could explain the increased susceptibility towards parasite infections during zinc deficiency." (PMID 36551176, 2022). "In conclusion, zinc deficiency aggravates inflammation by activating IRF/IL-23-mediated M1 macrophages and inhibiting GATA-3/IL-4 mediated M2 macrophages." (PMID 32331308, 2020). "During zinc deficiency, studies reported an imbalance between Th1 and Th2 cell differentiation, resulting in a diminished Th1 immune response with lowered IFN-γ and IL-2 production, whereas the Th2 cytokines (IL-4, IL-6, and IL-10) remain unaffected." (PMID 36551176, 2022). "A large category of cytokines, including IL-4, IL-6, interferon-g (IFN-g), TNF-α from innate immunity, and IL-2, TNF, and IFN-γ from adaptive immunity were found to be inhibited in production in patients with zinc deficiency." (PMID 35211497, 2022). "Serum changes associated with zinc deficiency also include an increase in Tumor Necrosis Factor-alpha (TNF-a) and pro-inflammatory cytokines and a decrease in anti-inflammatory cytokines such as interleukin-2 (IL-2) and interleukin-4 (IL-4)." (PMID 35353297, 2022). "For instance, zinc deficiency reduced production of Th1 cytokines, in particular IFN-γ, IL-2, and tumor necrosis factor (TNF)-α, whereas levels of Th2 cytokines IL-4, IL-6, and IL-10 were not affected." (PMID 29196724, 2017). "Our analysis of HBsAg-specific cytokines showed that prenatal zinc deficiency decreased the expression and secretion of IFN-γ, but not IL-4." (PMID 24069198, 2013). "Splenocytes of the pups from zinc deficiency and zinc supplemented groups produced lower levels of HBsAg-specific IFN-γ than the control group, whereas no remarkable changes in production of IL-4 in the three groups." (PMID 24069198, 2013).
acute lymphoblastic leukemia (7 papers, 2011 to 2025). Leukemia with an acute onset, characterized by the presence of lymphoblasts in the bone marrow and the peripheral blood. "Direct cytotoxicity and IL-4-induced apoptosis has been described with human B-lineage acute lymphoblastic leukemia cells as well as with a proportion of normal B cell progenitors." (PMID 31237933, 2019). "Furthermore, the genes encoding IFN-γ, GM-CSF, IL-4, IL-8, IL-2Rα, IL-2Rβ, IL-4R, IL-12Rβ, chemokines, chemokine receptors, and TNF were highly expressed in CIK cells under stimulation by acute lymphoblastic leukemia (ALL) cells." (PMID 25962508, 2015). "This novel partner cell line is a tri-hybrid of IL-4 secreting Th2 lymphoblast derived from a patient with acute lymphoblastic leukaemia (T), CD20+ B lymphoblast, also derived from a patient with acute lymphoblastic leukaemia (W), and IL-6 secreting peripheral blood-derived CD14+ monocyte (M)." (PMID 22373339, 2011).
acute respiratory distress syndrome (7 papers, 2019 to 2025). Progressive and life-threatening pulmonary distress in the absence of an underlying pulmonary condition, usually following major trauma or surgery. "It has been reported that IL-4, which is upregulated in acute lung injury or acute respiratory distress syndrome, along with apoptotic cells induces the tissue repair program of macrophages." (PMID 37615937, 2023). "Measurements and Main Results: IL-4 was elevated in human BAL from patients with acute respiratory distress syndrome, and its receptor was identified on patient blood neutrophils." (PMID 30849228, 2019). "In studies of acute respiratory distress syndrome (ARDS), EVs carrying IL-4 and IL-10 payloads reduced inflammation by decreasing pro-inflammatory cytokines such as IL-1 beta and TNF alpha while increasing anti-inflammatory metabolites." (PMID 40428144, 2025).
alopecia (7 papers, 2010 to 2024). Hair loss usually from the scalp. "Recent clinical case studies indicate that blocking IL4 and IL13 during AD-associated alopecia can reverse the hair loss indicating that various JAK-STAT inducers can feed into the HFSC intrinsic cascade." (PMID 39521937, 2024). "Kubo and colleagues reported that there was a positive correlation between the severity of the alopecia and the increase of Th1 cells, inversely proportional to the number of IL-4-producing Th2 cells." (PMID 25896390, 2015). "High serum levels of IL-4, IL-5, and IL-6 are also reported in patients with alopecia." (PMID 35273508, 2022). "Moreover, the pathogenesis of alopecia is complex, and different levels of IgE and IL-4 have been reported, depending on the various types of alopecia." (PMID 35895603, 2022). "High serum interleukin-4 (IL4) and low interleukin-12 (IL12) were observed in patients with alopecia showing a favorable response to DPC treatment." (PMID 33432924, 2021).
alopecia areata (7 papers, 2010 to 2025). Loss of scalp and body hair involving microscopically inflammatory patchy areas. "IL-4 levels were noticeably elevated in the alopecia areata group, with an average of 2.195 ± 4.366 pg/mL and a median of 0.880 pg/mL, compared to 1.105 ± 0.766 pg/mL and a median of 0.790 pg/mL in the control group." (PMID 40352276, 2025). "In analyzing cytokine and vitamin levels, we observed that individuals with alopecia areata exhibited elevated average levels of IL-4, IL-10, TNF-α, and IFN-γ, surpassing those of healthy controls." (PMID 40352276, 2025). "An increased serum level of IL-4 was described in patients with alopecia areata in comparison with the control group in numerous of previously published studies." (PMID 34943905, 2021). "A decreased expression of IL-4 mRNA was also observed in the peripheral blood mononuclear cells of patients with alopecia areata compared to healthy individuals." (PMID 34943905, 2021). "Based on previous observations, the role of the serum IL-4 in patients with alopecia areata remains ambiguous; thus, further studies are needed to evaluate the role of this cytokine in pathogenesis of the disease." (PMID 34943905, 2021). "While the blood analysis revealed higher average levels of IL-4, IL-10, and TNF-α in alopecia areata patients compared to healthy individuals, these differences were not statistically significant." (PMID 40352276, 2025). "Expanding on this, our study examined a broader range of cytokines, including IL-2, IL-4, IL-6, IL-10, IFN-γ, and TNF-α, to evaluate their potential correlation with the onset and progression of alopecia areata in blood assays." (PMID 40352276, 2025). "Although the variations in cytokines and vitamins such as IL-2, IL-4, IL-6, IL-10, TNF-α, and vitamins in the blood are insufficient to differentiate alopecia areata, we have observed a notable increase in IFN-γ and decrease in IgG4 levels among patients with this condition." (PMID 40352276, 2025).
amyotrophic lateral sclerosis (7 papers, 2018 to 2026). Amyotrophic lateral sclerosis (ALS) is a neurodegenerative disease characterized by progressive muscular paralysis reflecting degeneration of motor neurons in the primary motor cortex, corticospinal tracts, brainstem and spinal cord. "It was reported that IL-4 modulates microglia homeostasis and may attenuate slowly progressing neurodegenerative disorders (e.g., amyotrophic lateral sclerosis)." (PMID 38542084, 2024). "Interestingly, administration of IL-4 into an amyotrophic lateral sclerosis animal model was reported to induce microglia to adopt a slowly proliferating phenotype, which may corroborate a skewed microglia reactivity in these young animals." (PMID 35011699, 2022). "Whilst IL-4 delivery in animal models of multiple sclerosis, brain ischemia and spinal cord injury is neuroprotective, it has never been used in amyotrophic lateral sclerosis (ALS), a fatal disease featured by motor neurons (MNs) degeneration." (PMID 29445154, 2018).
cardiac hypertrophy (7 papers, 2021 to 2026). "This mechanistic study revealed that CCL17 recruits Th2 cells through binding to CCR4, thus perturbing T cell subset balance, promoting fibrotic-factor release (predominantly IL-4 and IL-17), and resulting in cardiac hypertrophy, fibrosis, and subsequent HF." (PMID 35687056, 2022). "Among the T-cell subpopulations, it appears that the CD4+ T-cells are the dominant immune mediators involved in the remodeling process that occurs in the postischemic myocardium and in maladaptive myocardial hypertrophy via the release of fibrosis promoting cytokines such as IL-4 and IL-13." (PMID 39273110, 2024).
chronic GVHD (7 papers, 2006 to 2024). "Lastly, HGF transfection inhibited IL-4 mRNA expression in the kidneys, liver, and spleen of chronic GVHD mice." (PMID 16859527, 2006). "Injection of DBA/2 spleen cells into BDF1 mice resulted in Th2 activation, as shown by the elevated IL-4 mRNA levels in target organs of mice with chronic GVHD." (PMID 16859527, 2006). "Chronic GVHD is inhibited by the injection of anti-IL-4 mAb, which suggests a critical role for IL-4 in this disease." (PMID 16859527, 2006). "By contrast, acute GVHD could be converted to a chronic GVHD phenotype with skewing of serum Ig to IL-4 dependent isotypes (IgG1, IgE) after IL-2 blockade." (PMID 38915570, 2024). "The PSGL1hi Th1, Th2, and Th17 cross-reactive autoreactive Trm cells interact with DCs and macrophages to mediate chronic GVHD pathogenesis via their production of cytokines such as TGF-β, IFN-γ, TNF-α, IL-4, IL-17, and IL-22." (PMID 34539630, 2021). "Expression of both IL-4 and IFN-γ mRNA was increased in the kidneys, liver, and spleen of untreated chronic GVHD mice 2 weeks after GVHD induction." (PMID 16859527, 2006). "We examined the effect of HGF gene transfection on IL-4 and IFN-γ mRNA expression levels in target chronic GVHD organs in the mouse." (PMID 16859527, 2006). "In a mouse model of chronic GVHD, it was reported that ex vivo cultured MDSCs could modulate chronic GVHD presumably by preventing thymic tissue damages and reducing the percentages of CD4+ T cells that produced IL-17 (Th17 cells) and IL-4 (Th2 cells)." (PMID 32528476, 2020). "However, HGF treatment inhibited IL-4 mRNA expression in chronic GVHD target organs, splenic B cell expansion, and autoantibody production in chronic GVHD mice." (PMID 16859527, 2006). "HGF gene transfection significantly inhibited the expression of IL-4 mRNA in these organs, while IFN-γ mRNA expression levels were not significantly altered between HGF-treated and untreated chronic GVHD mice." (PMID 16859527, 2006).
diabetic nephropathy (7 papers, 2015 to 2026). "Association of interleukins including IL-4 and IL-10 with diabetic nephropathy was also investigated in two studies." (PMID 26587547, 2015). "In OVA/Alum model, IL-4 was also shown to increase in PTX3-treated mice, so was IL-13, though not significant, in line with the results observed in animal model of diabetic nephropathy." (PMID 32938460, 2020).
fibrosarcoma (7 papers, 1993 to 2025). A malignant mesenchymal fibroblastic neoplasm affecting the soft tissue and bone. "Interestingly, COX-2-fibrosarcomas exhibited increased expression of Il4 and Ido1 encoding interleukin-4 and Ido, whereas the expression of Ifng encoding interferon-gamma was significantly reduced." (PMID 25501829, 2014). "In resistant tumor models spanning multiple cancer types—including colon, breast, lung, fibrosarcoma, and bladder—higher IL-4 production has been identified as a characteristic feature, distinguishing resistant cells from their non-resistant counterparts." (PMID 40507238, 2025). "Gata3 leads to its overexpression in a positive feedback loop while simultaneously driving the expression of other genes, including interleukin-4 (IL-4), IL-5, and c-musculoaponeurotic fibrosarcoma (c-Maf) TF, of which the latter helps to induce further expression of IL-4." (PMID 36831302, 2023). "Here we demonstrate that the weakly immunogenic murine fibrosarcoma FS29 had reduced growth rate and in some cases was rejected by syngeneic animals, when modified to secrete either IL-2 or IL-4, but not IL-5." (PMID 8347485, 1993).
Graves disease (7 papers, 2011 to 2025). Graves' disease is an autoimmune disorder that leads to overactivity of the thyroid gland (hyperthyroidism).It is caused by an abnormal immune system response that causes the thyroid gland to produce too much thyroid hormones. "In Graves’ disease, Th2 lymphocytes are infiltrated and IL-4 and IL-10 are produced, causing the expression of anti-apoptotic molecules and also, their resistance to apoptosis through CD95." (PMID 33193078, 2020). "The role of IL-4 in the pathogenesis of Graves’ disease (GD) remains controversial." (PMID 40895623, 2025). "Graves’ disease occurs when a high proportion of Th2 cells are present and secrete the cytokine IL-4, and a complete lack of IL-4 has been shown to eliminate Graves’ disease in animal model." (PMID 25854833, 2015).
hypothyroidism (7 papers, 2011 to 2024). Abnormally low levels of thyroid hormone. "Linear regression analyses showed that none of the selected variables was significantly associated with IL-4 concentrations, except for hypothyroidism." (PMID 36552602, 2022). "Hypothyroidism patients had increased C-reactive protein (CRP), interleukin-2 (IL-2), IL-4, IL-10, and tumor necrosis factor (TNF)-α levels." (PMID 39185088, 2024). "We found that the CRP, IL-2, IL-4, IL-10, and TNF-α levels were greater in the hypothyroidism group than in the control group." (PMID 39185088, 2024). "The serum CRP, IL-2, IL-4, IL-10 and TNF-α levels in the hypothyroidism group were greater than those in the control group (P < 0.05)." (PMID 39185088, 2024).
measles (7 papers, 2009 to 2024). A highly contagious viral infection caused by the measles virus. "Cellular IL-4 production against measles showed a gestational increase but was also significantly reduced in second trimester pregnancies compared to healthy controls (p = 0.0194)." (PMID 28966619, 2017). "Type 2 polarization of cytokine responses occurs during the late stages of measles with an increase in the secretion of interleukin 4 (IL-4) and a decrease of IL-2 and interferon γ (IFN-γ) levels." (PMID 19319188, 2009). "A Th1 cytokine profile, with elevations in peripheral blood gamma interferon (IFN-γ) and interleukin-2 (IL-2), is present during the measles prodrome, whereas measles convalescence is characterized by elevations in Th2 cytokines, such as interleukin-4 (IL-4) and interleukin-5 (IL-5)." (PMID 32085446, 2020). "Scarce studies on measles lung LIR indicated depletion of IL-10+ and IL-12+ cells in infected children; however, there was a greater number of IL-1+, IFN+, and IL-4+ cells." (PMID 30936878, 2019). "The lack of impact of HCMV infection on measles-specific innate pro-inflammatory cytokines IL-1β and TNF, the Th1 cytokine IFN-γ, the Th2 cytokine IL-4 and the anti-inflammatory cytokine IL-10 is encouraging." (PMID 32582177, 2020).
osteonecrosis (7 papers, 2017 to 2025). A none disease characterized by death of bone tissue due to a lack of blood supply. "In this study, we successfully developed engineered exosomes (DS-exo@A2M), which promote bone repair in osteonecrosis of the femoral head (ONFH) by regulating IL-4-mediated M2 macrophage polarization and reshaping the inflammatory microenvironment." (PMID 41203607, 2025). "Previous studies have shown that inflammatory cytokines are increased during the development of steroid-induced osteonecrosis, such as IL-1, IL-2, IL-4, IL-6, IL-10, GM-CSF, IFN-γ, and TNF-α." (PMID 28167850, 2017). "In addition, we have reported that the injection of IL4-MSCs significantly decreased the number of empty lacunae compared to MSCs in a model of corticosteroid induced osteonecrosis but resulted in less osteogenesis in vivo." (PMID 34821731, 2021). "Restoration of butyrate through FMT or sodium butyrate supplementation alleviated osteonecrosis by modulating inflammatory cytokines, reducing TNF-α and IL-2, and increasing IL-4 expression." (PMID 40510588, 2025). "Except for IL-4 and IL-1RA, none of the other cytokines (e.g., VEGF, GRO-α, Trail, MIG, IL-7, IL-17) were shown to be associated with the risk of osteonecrosis in the IVW primary MR analysis or other secondary analyses." (PMID 38357652, 2024). "Except for IL-4, none of the other cytokines (e.g., VEGF, GRO-α, Trail, MIG, IL-7, IL-17) were shown to be associated with the risk of osteonecrosis in the IVW primary MR analysis or other secondary analyses." (PMID 38357652, 2024).
osteosarcoma (7 papers, 2012 to 2025). A usually aggressive malignant bone-forming mesenchymal neoplasm, predominantly affecting adolescents and young adults. "Osteosarcoma had 25 significant relationships, notably including IL-4/IL-1β (r2 = 0.58, p = 0.000048), IL-12 p40/IL-4 (r2 = 0.47, p = 0.0015), CXCL5/IL-27 (r2 = −0.48, p = 0.001), CXCL14/IL-15 (r2 = 0.66, p = 0.0000021)." (PMID 41008853, 2025). "This is in agreement with findings by others showing that IL-4 stimulates ALP activity in a dose-dependent manner in cultured human osteoblasts and in the human osteosarcoma cell line MG63." (PMID 27667999, 2016). "To examine whether endogenous expression of IL13RA1-LOR1a can affect the ability of the cells to sense IL-4 or IL-13, we targeted its expression in U2OS osteosarcoma cells, which respond to stimulation by up-regulating CCL26." (PMID 40614216, 2025). "To investigate the role of CD24 in regulating the macrophage-mediated immune response in OS, we treated bone marrow-derived macrophages (BMDMs) with IL-4 to generate M2-like macrophages and cocultured these less phagocytic macrophages with the GFP+ K7M2 osteosarcoma cell line for 36 h." (PMID 36596773, 2023).
peripheral nerve injury (7 papers, 2012 to 2025). Injury to a peripheral nerve. "Anti-inflammatory interleukins, such as IL-4, IL-10, and IL-13, play a critical role in enhancing the repair microenvironment following peripheral nerve injury." (PMID 41573554, 2025). "Downregulation of pro-inflammatory cytokines by an increased differentiation into anti-inflammatory M2 macrophages under the influence of IL-4 is suggested to play a role in reducing hypersensitivity after peripheral nerve injury." (PMID 37138291, 2023). "Preclinical literature suggests that IL-4 is a key mediator in reducing neuropathic pain behaviours in models of peripheral nerve injury." (PMID 34224495, 2022). "Interleukin 4 (IL-4) produced by peripheral nerve injury has exclusive anti-inflammatory and anti-nociceptive actions." (PMID 35295524, 2021). "For example, IL-4 was shown to promote motor neuron survival through STAT6 signaling in a model of peripheral nerve injury, while in dorsal root ganglion cells, IL-4 enhanced axonal regeneration through the stimulation of local neurotrophin secretion." (PMID 29064422, 2017). "The cytokines IL6, TNF, IL10, IL2, and IL4 are all immunomodulatory factors, among which TNF and IL-6 have been confirmed to be involved in the pathological process of peripheral nerve injury." (PMID 33299447, 2020). "The IL-4 expression was hardly detectable at the mRNA level in our model of acute peripheral nerve injury and did not seem to be induced." (PMID 22818207, 2012).